DHCR24 (24-dehydrocholesterol reductase)
Diseases named in the same sentence as DHCR24 in open-access papers (continued):
Sharing a sentence is not in itself a finding about the gene and the disease.
tauopathies (2 papers, 2021 to 2022). "Taking together, our results firstly demonstrated that the decrease of plasma membrane cholesterol mediated by DHCR24 deficiency might contribute to the tauopathy in AD and other tauopathies." (PMID 33967735, 2021). "Furthermore, the decrease of plasma membrane cholesterol mediated by DHCR24 deficiency might contribute to the tauopathy in AD and other tauopathies, at least partly by membrane lipid raft-mediated signaling mechanism." (PMID 33967735, 2021). "To further uncover the role of autophagy in the tauopathy induced by DHCR24 knock-down, we examined the regulation of autophagic activity in the knock-down or knock-in of DHCR24 by transmission electron microscope (TEM) and western blot analysis." (PMID 33967735, 2021). "In our experiment, we will focus on the effect of DHCR24 on the tau hyperphosphorylation at some sites such as Thr181, Ser199, Thr231, Ser262, Ser256, Ser396, and autophagy, in order to elucidate the relationship between DHCR24 downregulation and tauopathy." (PMID 33967735, 2021). "Therefore, to elucidate a molecular mechanism link between DHCR24 and tauopathy will help to clarify the role of DHCR24 in the pathogenesis of AD and other tauopathies." (PMID 33967735, 2021). "Herein, we firstly found that DHCR24 knockdown can lead to tau hyperphosphorylation in the astrocyte itself by activating lipid raft-dependent Ras/MEK/ERK signaling, which might contribute to the pathogenesis of AD and other degenerative tauopathies." (PMID 35804281, 2022). "We explored whether DHCR24 downregulation affects tau hyperphosphorylation in astrocytic tauopathy through the activation of lipid rafts/caveolae-dependent RAS/MEK/ERK signaling, which could contribute to the tauopathy in AD and other neurodegenerative diseases." (PMID 35804281, 2022). "Therefore, our findings support that DHCR24 knockdown can lead to tau hyperphosphorylation in the astrocyte itself by activating membrane lipid raft-dependent Ras/ERK/ERK signaling, which might contribute to the pathogenesis of AD and other degenerative tauopathies." (PMID 35804281, 2022).
astrocytoma (1 paper, 2024). "This is in line with the decrease in DHCR24 expression demonstrated with lipid extracts of H. elongata and S. fusiforme on the transcriptional level in an astrocytoma cell line." (PMID 38892548, 2024).
cardiac dysrhythmias (1 paper, 2024). "It was shown recently that the licensed drug amiodarone, a multichannel blocker for the treatment of cardiac dysrhythmias, is also capable of lowering cholesterol biosynthesis in human cell lines by direct inhibition of the 24-dehydrocholesterol reductase (DHCR24)." (PMID 38935126, 2024).
cervical adenocarcinoma (1 paper, 2015). An adenocarcinoma arising from the cervical epithelium. "Surface expression of DHCR24 was also not detected in the cervical adenocarcinoma-derived cell line HeLa, even when intracellular DHCR24 protein was overexpressed." (PMID 25875901, 2015).
cervical cancer (1 paper, 2025). A primary or metastatic malignant neoplasm involving the cervix. "24-dehydrocholesterol reductase (DHCR24), another critical biosynthetic enzyme, is effectively targeted by hucMSC-sEV-delivered miR-370-3p, which suppresses cervical cancer progression via cholesterol homeostasis disruption." (PMID 40722703, 2025).
cholangiocarcinoma (1 paper, 2025). A carcinoma that arises from the intrahepatic biliary tree (intrahepatic cholangiocarcinoma) or from the junction, or adjacent to the junction, of the right and left hepatic ducts (hilar cholangiocarcinoma). "This revealed tumor‐specific potential markers, several of which have been previously implicated in tumor biology (e.g., F2RL2 in gynecological cancers, DHCR24 and RAG1 in thymic carcinoma, PTGDS in cholangiocarcinoma)." (PMID 40784724, 2025).
dermopathy (1 paper, 2021). "Global knockout (KO) of Dhcr24 in mice recapitulates the biochemical phenotype, but pups die within 24 h from a lethal dermopathy, limiting its utility as a disease model." (PMID 33524375, 2021). "We sought to generate a viable mouse model with tissue-specific deletion of Dhcr24 to avoid the lethal dermopathy." (PMID 33524375, 2021).
developmental delay (1 paper, 2023). "Here, we describe a new patient with severe developmental delay, epileptic encephalopathy, spastic tetraparesis, cataracts, and several dysmorphic features, harboring the novel homozygous missense variant NM_014762.4:c.506T>C, NP_055577.1:p.M169T in the DHCR24 gene." (PMID 38239854, 2023).
diffuse large B-cell lymphoma (1 paper, 2025). "DHCR24 is a direct target of the stem cell regulator SOX9, and in a diffuse large B‐cell lymphoma (DLBCL) cell line xenograft model, knockdown of SOX9 resulted in reduced DHCR24 levels, decreased cholesterol content, and reduced tumor load." (PMID 40145543, 2025).
hepatitis C (1 paper, 2014). "A number of recent researches have shed light on unexpected and new roles of desmosterol and DHCR24 in metabolic diseases including hepatitis C." (PMID 24718268, 2014).
hepatoblastoma (1 paper, 2015). Hepatoblastoma (HB) is a malignant hepatic tumor and is the most common pediatric liver cancer. "Overexpression of DHCR24 was observed in HCC and hepatoblastoma (HB) cell lines but not in hepatic cell lines derived from normal liver tissue." (PMID 25875901, 2015).
memory impairment (1 paper, 2021). "Whether the overexpression of DHCR24 can reverse the memory impairment caused by AD in animal models could become an important part of future studies in this field." (PMID 34671194, 2021). "In addition, we reported, for the first time, that cholesterol loss caused by inhibiting its de novo synthesis through the inhibition or knockdown of DHCR24 resulted in memory impairment in the experimental animal model." (PMID 34671194, 2021).
periodontitis (1 paper, 2024). An acute or chronic inflammatory process that affects the tissues that surround and support the teeth. "DHCR24, here, downregulated at the mRNA and protein levels in the T2DM-related periodontitis, has antiapoptotic functions and inhibits the generation of intracellular reactive oxygen species and LPS-induced osteoclastogenesis." (PMID 38241313, 2024).
prostate tumors (1 paper, 2022). "Expression of DHCR24 is higher in PCa tumors as compared to adjacent normal prostate tissues and the expression of DHCR24 is regulated by androgen in prostate tumors." (PMID 35197069, 2022).
pulmonary fibrosis (1 paper, 2025). Chronic progressive interstitial lung disorder characterized by the replacement of the lung tissue by connective tissue, leading to progressive dyspnea, respiratory failure, or right heart failure. "Notable pathways negatively associated with SOFA score change were response to elevated platelet cytosolic Ca2+ signaling, docosahexaenoic acid (DHA) signaling, 24‐dehydrocholesterol reductase (DHCR24) signaling, pulmonary fibrosis idiopathic signaling, and wound healing signaling." (PMID 40170544, 2025).
Q fever (1 paper, 2022). A bacterial infection caused by Coxiella burnetii.
serous ovarian cancer (1 paper, 2026). "Importantly, this metabolic phenotype was independent of molecular subtype, supporting the view that blocking cholesterol biosynthesis, possibly via the upregulated enzymes DHCR7 or DHCR24, could be a promising therapeutic strategy for high-grade serous ovarian cancer." (PMID 41233595, 2026).
skin tumours (1 paper, 2022). "A study investigating the role of Rac1 activity in the malignant progression of sebaceous skin tumours identified DHCR24 as a target gene." (PMID 35626014, 2022).
urogenital neoplasm (1 paper, 2017). Tumors or cancer of the UROGENITAL SYSTEM in either the male or the female. "3β-Hydroxysteroid-Δ24 reductase (DHCR24), the final enzyme of the cholesterol biosynthetic pathway, has been associated with urogenital neoplasms." (PMID 28112250, 2017).
viral infections (1 paper, 2021). "DHCR24 is an endoplasmic reticulum (ER) protein that facilitates the final step of cholesterol biosynthesis and is connected to ER stress in viral infections." (PMID 34335605, 2021).
cancer (33 papers, 2010 to 2026). A tumor composed of atypical neoplastic, often pleomorphic cells that invade other tissues. "The hub genes ATP6AP2, ACTR1A, SYNM, ZMYND8, CAMTA1, SLC39A3, and DHCR24, are associated with cancer development and progression." (PMID 39757707, 2025). "3β-hydroxysterol Δ24-reductase (DHCR24) is closely associated with the progression of various malignant tumors, but its role in OC remains unexplored." (PMID 41050066, 2025). "Additionally, a close association has been reported between DHCR24 upregulation and malignant behaviors in cancer cells." (PMID 39830660, 2024). "Integrating a large-scale pan-cancer study comparing 1739 cell lines of different tumor origins confirmed high DHCR24 and DHCR7 mRNA levels in HGSOC (Fig. EV6C,D)." (PMID 41233595, 2026). "During cancer development, DHCR24 has been demonstrated to be aberrantly expressed in various cancers, including metastatic melanoma, bladder cancer, and salivary adenoid cystic carcinoma, although its specific mechanisms in OC remain to be fully elucidated." (PMID 41050066, 2025). "DHCR24 is reported to function as a hydrogen peroxide scavenger and plays an oncogenic role in various cancers." (PMID 38671459, 2024). "DHCR24 is thought to play a significant role in cancer, so U18666A has also been tested in cancer models." (PMID 38672427, 2024). "DHCR24, a pivotal enzyme of the cholesterol biosynthetic pathway, has been characterized as a reactive oxygen species (ROS) scavenger in types of cancers." (PMID 35501301, 2022). "Significantly, five of these genes (Mvd, Sqle, Cyp51, Hsd17b7, and Dhcr24) are within the core biochemical processes of the mevalonate pathway, an important target for anti-cancer therapy." (PMID 32477466, 2020). "The role of DHCR24 has been well-characterized in various cancers." (PMID 41050066, 2025). "Interestingly, some novel BC related proteins (STEAP4, CLPTM1L, TMEM41A, DHCR24, etc.) were also discovered, which have been reported to be involved in other cancer types." (PMID 33842315, 2021). "Previous studies have shown that DHCR24 expression is deregulated in different types of cancer." (PMID 28112250, 2017). "Therefore, we hypothesized that Rap1-AKT signaling is downstream of DHCR24 regulation and positively related to cancer stem cells." (PMID 38775844, 2024). "Therefore, in some types of cancer cells, surface expression of DHCR24 might be induced by certain stimuli." (PMID 25875901, 2015). "We therefore targeted DHCR7 and DHCR24, as both are non-essential cancer genes and contain PRDM9 motif at their promoters." (PMID 41397959, 2025). "CNR1, DHCR24, DPP6, and MEF2C were strongly correlated with disturbances in executive functioning, episodic memory, and visuospatial functioning, which deregulate expression in multiple human cancers contributing to the antioxidant and repairing activity." (PMID 36518809, 2022). "We further verified the expressions of the oxidative stress-responsive genes and the cholesterol biosynthesis-related genes using qPCR in the GBM cancer cells and recorded an increase in the mRNA levels of HMGCR, HMCGS1, DHCR24, GSR, GSTM2 and GCLC after MPT0L145 treatment in U87MG and M059K cells." (PMID 34885226, 2021).
cancer (continued). "Importantly, we observed an inverse correlation between circulating HDL-c and transcript levels of Phgdh and five enzymes of the mevalonate pathway (Mvd, Sqle, Cyp51, Hsd17b7, and Dhcr24) in tumor bed, suggestive of an inhibitory role for apoA-I/HDL in cancer cell metabolism." (PMID 32477466, 2020).
tumor (29 papers, 2012 to 2026). "In the study, we proved that Q7 decreased DHCR24 expression to interface AKT-kinase to induce caspase cascade to cause tumor cell apoptosis and mTOR-associated migration regulators." (PMID 36483599, 2022). "The up-regulation of DHCR24 is associated with invasiveness and disease recurrence in urothelial cancer, which suggests a crucial role for this protein in tumor progression." (PMID 28112250, 2017). "Based on its association with aggressive tumor behaviors, DHCR24 may serve as a novel potential prognostic marker." (PMID 28112250, 2017). "A study also reveals that DHCR24 participates in the generation and progression of tumor cells by regulating intracellular reactive oxygen species." (PMID 41050066, 2025). "The nude mouse tumor formation experiment demonstrated that inhibiting DHCR24 suppresses the in vivo growth of OC cells." (PMID 41050066, 2025). "To molecularly define potential mechanisms by which DHCR24 influences the tumor immune microenvironment, we constructed a protein–protein interaction (PPI) network centered on DHCR24." (PMID 41514881, 2025). "DHCR24 plays a crucial role in tumor development and is also identified as a biomarker for tumor diagnosis." (PMID 39830660, 2024). "DHCR24 deficiency effectively increased sensitivity to DDP, as indicated by reduced tumor volume and weight." (PMID 39830660, 2024). "In the present study, we found that lowering intracellular cholesterol by knocking down DHCR24, the limiting synthetase, impaired tumor cell proliferation and migration and abrogated the ability to xenotransplant tumors." (PMID 38775844, 2024). "Membranous immunoreactivity of SR-B1 (p = 0.0289), and cytoplasmic immunoreactivity of ACAT1 (p = 0.0004), ACAT2 (p < 0.0001), HSL (p < 0.0001) and DHCR24 (p < 0.0001) were significantly higher in compact than in clear tumor cells." (PMID 35216289, 2022). "More importantly, ELISA analysis showed that DHCR24 enzyme activity was strongly decreased in xenograft tumour samples from GD-treated animals." (PMID 32958824, 2020). "To further clarify the mechanism by which GD inhibited tumour growth in vivo, we analysed the expression levels of Ki-67 and DHCR24 in tumour samples by immunohistochemical staining." (PMID 32958824, 2020). "A Random Forest Classifier model showed that, in eight of the nine tumor cohorts, these patterns were largely determined by a small subset of transcripts, comprised of DHCR24, HMGCS2, PMVK and ACAT1/2." (PMID 31242205, 2019). "Although DHCR24 has been found to take part in tumor progression, the expression pattern of DHCR24 in EC is still not fully elucidated." (PMID 28112250, 2017). "Furthermore, tumor volume, tumor growth rate, and weight increased significantly in the DHCR24 overexpression group, suggesting that DHCR24 overexpression promotes OC cell proliferation in vivo." (PMID 41050066, 2025). "However, DHCR24 silencing notably decreased both Ki-67 and DHCR24 expression in tumor tissues upon DDP treatment." (PMID 39830660, 2024). "And with the assistance of RNA-seq analysis, we efficiently proved the anti-tumor mechanisms of Q7 which could inhibit the tumorgenicity of HEC-1-A cells by suppressing DHCR24 expression to mediate the AKT-modulated signal pathway." (PMID 36483599, 2022). "The results are in line with previous reports showing the important role of DHCR24 in tumour growth and metastasis, which also predict that DHCR24 might become an effective target in HCC therapy." (PMID 32958824, 2020). "A significant correlation was observed between DHCR24 overexpression and aggressive tumor behaviors in EC, which suggests that DHCR24 may play a pivotal role in EC tumor development." (PMID 28112250, 2017). "Elevated expression DHCR24 was observed in different neoplastic diseases." (PMID 28112250, 2017).
tumor (continued). "Therefore, DHCR24 expression could serve as a functional readout of a tumor’s metabolic-immune state, aiding in molecular subtyping and identifying tumors reliant on this pathway." (PMID 41514881, 2025). "This could have caused the discrepancy between DHCR24 expression and de novo pathway activity, but it is also important to note that we could not separately analyze the clear and compact tumor cells in our present study using GC-MS." (PMID 35216289, 2022). "Surprisingly, DHCR24 knockdown enhanced malignant phenotypes in MCF7 cells, contrasting its pro-tumor role in patients." (PMID 41514881, 2025). "With careful titration, the modified MC38 cell line had normal Dhcr24 level while 2-4-fold increased expression of upstream genes (Figure EV4B), which mimicked the pattern of MSS CRC tumor." (PMID 38177537, 2024). "In normal lung tissue adjacent to the tumor, CRABP2, DHCR24, and AK4 were observed in bronchial epithelial cells, but not in alveolar pneumocytes." (PMID 37004157, 2023). "For example, SC4MOL and NSDHL inactivation sensitizes tumor cells to EGFR inhibitors, and DHCR24 heterozygous knockout in mice reduces cholesterol levels without causing health problems." (PMID 35386193, 2022). "Integrated analysis resolved this paradox, revealing that DHCR24 promotes BC progression non-cell-autonomously by remodeling an immunosuppressive tumor microenvironment, rather than by intrinsically driving cancer cell proliferation." (PMID 41514881, 2025). "On the other hand, although the role of DHCR24 overexpression in tumor cells is still not clear, it has been reported that DHCR24 protects cells from endoplasmic reticulum stress‐derived apoptosis in neurons, suggesting that it has an anti‐apoptotic function." (PMID 37004157, 2023). "Notably, DHCR24 expression was positively correlated with SRSF3 and CA199, a tumor marker, in this corpus of CRC tissues." (PMID 35501301, 2022). "Significantly downregulated genes in NHT tumours (DESeq comparison; Benjamini-Hochberg P <0.05) were typically androgen responsive (for example, TMPRSS2, KLK3, BMPR1B, TPD52) or steroidogenesis-related (for example, DHCR24, SCD), consistent with a reduction in androgen receptor activity." (PMID 25155515, 2014). "DHCR24 promotes tumor proliferation, apoptosis resistance, and invasion through cholesterol biosynthesis, and activates the PI3K‐AKT signaling pathway, while RAG1, reexpressed by tumor‐infiltrating T cells—may facilitate immune evasion via TCR specificity remodeling." (PMID 40784724, 2025).